IL7 (interleukin 7)
Diseases named in the same sentence as IL7 in open-access papers (continued):
Sharing a sentence is not in itself a finding about the gene and the disease.
breast carcinoma (continued). "For instance, there is observed a relapse-free survival and the inhibition of pulmonary metastasis nodules by treating with IL-7 and IL-15 after radiofrequency thermal ablation (RFA) in mammary carcinoma." (PMID 31915416, 2019). "Intralesional injection with IL-7 and IL-15 in RFA-treated animals can also reduce the proportion of MDSC present in the spleen in murine mammary carcinoma." (PMID 25955647, 2015). "The potential therapeutic possibilities of targeting lymphangiogenic factors in breast cancer using VEGFR-3 antagonists, COX-2 antagonists, IL-7 antagonists and others have been the subject of recent intense investigation." (PMID 18325094, 2008). "In addition, studies investigating the combined ablation of additional IL-2 family members have also been undertaken, injection of IL-7 and IL-15 after RFA effectively inhibits tumor growth in a mouse breast cancer model." (PMID 38833177, 2024). "Through a combination of RNA sequencing analysis, database screening and invasion assays we identified IL7/IL7R and IL15/IL15R as pairs of chemokines and receptors with potential roles in promoting chemotactic migration of breast cancer cells with mesenchymal properties towards the lymphatics." (PMID 38055067, 2023). "The results suggested that IL7 and IL15 could function as chemotactic factors for breast cancer cells with mesenchymal properties." (PMID 38055067, 2023). "This indicated that IL7 and IL15 could act as chemoattractants for breast cancer cells with mesenchymal properties." (PMID 38055067, 2023). "Overexpression of IL7 and the IL7R correlates with invasion and poor prognosis in breast cancer." (PMID 38055067, 2023). "Consequently, the IL-7/HGF/LIF/VEGF cluster has been identified as a functional module that orchestrates multiple processes, including development, angiogenesis, stem cell maintenance, and the establishment of an immunosuppressive phenotype within the breast cancer microenvironment." (PMID 41597220, 2026).
Autoimmunity (44 papers, 2010 to 2025). The occurrence of an immune reaction against the organism's own cells or tissues. "Since IL-7 plays a role in both predisposing to autoimmunity and in perpetuating autoimmune inflammation, targeting IL-7/IL7R signaling appears to be an attractive therapeutic option for preventing CRC." (PMID 27866242, 2017). "The IL-7 signaling pathway is involved in normal lymphocyte development, peripheral T cell homeostasis, the regulation of immune tolerance, and mechanisms related to autoimmunity; it is also closely associated with the progression of various tumor types." (PMID 41360767, 2025). "Increased IL-7 production plays a role in the predisposition to autoimmunity and inflammation." (PMID 32370284, 2020). "We speculate that the risk of developing autoimmunity after IL-7 treatment may vary dependent on individual clinical history, genetic predisposition, and the administration regimen." (PMID 29506153, 2018). "In addition, the presence of sCD127 has been associated with enhanced IL-7-mediated homeostatic proliferation and exacerbation of existing T-cell-derived autoimmunity." (PMID 29261677, 2017). "Three independent studies showed that elevated sIL-7R is associated with an increased risk of to develop autoimmunity, a situation which maybe at first glance counter-intuitive: since soluble IL-7R may bind free IL-7 and neutralizes its effects." (PMID 24946690, 2014). "On the other hand, genome wide association studies (GWAS) have identified a number of potential genes associated with MS including receptors for IL-7 (IL-7RA) and IL-2 (IL-2RA); besides, IL-2 and IL-7 pathways have previously been demonstrated to regulate autoimmunity and EAE in animal models." (PMID 24174969, 2013). "Nonetheless, there have been recent efforts focused on targeting memory T cells in recurrence autoimmunity, with strategies such as blocking IL-7 and IL-15 signaling showing promise in reversing new-onset autoimmune diabetes in NOD mice." (PMID 40182604, 2025). "Membrane-bound IL-7R mediates IL-7 signalling, while soluble IL-7R provides regulatory control, amplifying IL-7 signalling and enhancing autoimmunity." (PMID 38675377, 2024). "IL-7 was also shown to be involved in the generation and maintenance of T-cell autoimmunity in T1DM and to provide essential signals for the generation of human memory stem T cells from naive precursors." (PMID 33003647, 2020). "IL-7 is, therefore, suggested to play a pivotal role in the development and recurrence of autoimmunity and graft failure." (PMID 31024566, 2019). "Regulation of T-cell mediated autoimmunity by IL-7 has been reported to be inversely proportional to the extent of its glycosylation." (PMID 29391066, 2018). "Although further research is needed to identify such signals in IL-7 cultures, our data support a role for IL-7 in T cell-driven immunopathology in chronic and persistent infections, coinfections, or autoimmunity." (PMID 29506153, 2018). "From this, they concluded that increased plasma concentrations of sIL-7R supported generation of autoimmunity by promoting IL-7-dependent T cells." (PMID 28582466, 2017). "IL-7-mediated homeostatic proliferation T cell clones have gained increasing interest in the pathogenesis of type 1 diabetes and in autoimmunity recurrence post pancreas or islet transplantation." (PMID 26983628, 2016). "In line with these mouse data, in the DC/T-cell co-cultures we observed potent additive effects of IL-7 and TSLP on production of Th17-associated cytokines IL-17, IL-21 and IL-22 that can strongly stimulate autoimmunity." (PMID 26110994, 2015). "IL7 is fundamental to development of IL17 producing cells and plays a role in maturation of auto-reactive T-cells, it is also associated with autoimmune disorders including multiple sclerosis and type-1 diabetes." (PMID 25933188, 2015).
Autoimmunity (continued). "In multiple sclerosis, aberrant splicing of exon 6 was shown to increase the production of sIL-7R and that sIL-7R is able to potentiate IL-7 bioactivity and to promote autoimmunity." (PMID 25533722, 2014). "Interleukin-7 (IL-7) is a cytokine essential for T-cell lymphopoiesis, survival and polarization with an emerging role in autoimmunity." (PMID 25533722, 2014). "In summary, our results provide new insights into the regulation of intestinal homeostasis and have important implications for the design of clinical protocols targeting the IL-7/IL-7R signaling pathway to treat T cell-mediated autoimmunity and cancer." (PMID 22384106, 2012). "Increased T cell numbers and signs of autoimmunity were detected at higher IL-7 doses, whereas a higher competition for IL-7 via IL-7Rα overexpression led to decreased T cell numbers." (PMID 22194871, 2011). "The ultimate effect of IL-7 excess in autoimmunity is a reduction of the activation threshold of autoreactive T cells, which, when superimposed on a predisposed genetic background, leads to disease enhancement." (PMID 22102903, 2011). "A marked decrease in IL-7 may indicate utilization or dysregulation of IL-7–dependent T- and B-cell populations during immune activation, thereby contributing to autoimmunity." (PMID 41394871, 2025). "In addition, targeted therapy of the IL-7/IL-7Rα pathway has shown therapeutic effects in multiple autoimmune mouse models, indicating the important role of IL-7 in autoimmune inflammation." (PMID 40313966, 2025). "This potentiation effect exacerbates EAE, highlighting the role of IL-7 in promoting autoimmunity." (PMID 40313966, 2025). "The administration or neutralization of IL-7 may enable the modulation of immune function in individuals with lymphocyte depletion or autoimmunity." (PMID 38742104, 2024). "In order to explore this concept, we examined whether constraints on IL-7 signaling in high versus low competition settings would influence the development of autoimmunity." (PMID 29075267, 2017). "Finally, we discuss the actions of proinflammatory cytokines that breach immune tolerance and induce autoimmunity, which include IL-7, IL-12, IL-21, and IL-23." (PMID 27574641, 2014). "Furthermore, dysregulated IL-7 expression or activation of CD127 were found in patients with autoimmune conditions, suggesting that IL-7 supports the function of pathogenic effector cells in autoimmunity." (PMID 29506153, 2018). "Thus, together with available data, our results suggest that IL-7 might awaken auto-reactive T cells, or pathogen-specific effector T cells with cross-reactivity to self-Ag, hence contributing to autoimmunity." (PMID 29506153, 2018). "In this review, we discuss recent evidences and novel findings on the role of IL-7 mediated homeostatic T cell proliferation in the process of beta-cell destruction and evidences of how targeting IL-7 and its receptor could be an innovative and effective strategy to control beta-cell autoimmunity." (PMID 26983628, 2016). "Conversely, increased serum levels of IL-7 and/or dysregulated activation of CD127 are reported in patients with autoimmune conditions, including multiple sclerosis, rheumatoid arthritis, type-I diabetes, inflammatory bowel disease, and psoriasis." (PMID 29506153, 2018). "Taken together, these data suggest that limitation of LIP potential by inhibiting the ability of T cells to respond to IL-7-mediated signals in situations of high but not low competition for finite pMHC can prevent the loss of weight associated with the pathology of LIP-driven autoimmunity." (PMID 29075267, 2017). "This is the first study to assess the combined roles of IL-7 and TSLP in autoimmunity and shows that both cytokines play a specific pro-inflammatory role during experimental arthritis." (PMID 26110994, 2015).
Autoimmunity (continued). "The lack of IL-7–IL-7 receptor(R)-mediated signaling compromises lymphoid development, whereas increased signaling activity contributes to the development of chronic inflammation, cancer and autoimmunity." (PMID 34276694, 2021). "Abrogation of IL-7-dependent signaling results in a SCID phenotype characterized by the lack of T cells and profound immunodeficiency, while abrogation of IL-2-dependent signaling leads to inflammation, multi-organ lymphocyte infiltrates, and autoimmunity in mice and possibly in humans." (PMID 23383227, 2013). "Earlier evidence of IL-21 (or a combination of IL-21 and IL-7) as a potential biomarker has not been substantiated in larger prospective cohorts, further complicated by the inability of currently available IL-21 ELISA kits to predict autoimmunity after alemtuzumab." (PMID 26204829, 2015). "The excess IL-7 is not, however, consumed by CD4–CD8– T cells due to permanent down-regulation of IL-7Rα (CD127), but instead supports proliferation of autoreactive T cells and progression of autoimmunity." (PMID 22102903, 2011).
melanoma (42 papers, 1994 to 2026). A malignant, usually aggressive tumor composed of atypical, neoplastic melanocytes. "In melanoma patients, lower levels of IL-7 are associated with CD8+ T-cell exhaustion, as shown by decreased soluble CD127 (sCD127) levels and altered CD127 expression." (PMID 40636453, 2025). "IL-7 is linked to disease progression in melanoma, with lower serum levels observed in patients, especially those with BRAF mutations." (PMID 40636453, 2025). "Previous work has demonstrated an association of genetic expressions, as of a variant of the IL-7 gene, with an increased risk of irAE development in melanoma patients undergoing ICI therapy." (PMID 40155873, 2025). "Genetic analyses in a cohort of patients with melanoma receiving immunotherapy reveal that variants in IL7 are associated with immune-related adverse events and highlight the role of B cells in mediating toxicity." (PMID 36526722, 2022). "The allele rs16906115 is intronic to IL7, and, unexpectedly, we found robust expression of IL7 in B cells, which is markedly induced in patients with melanoma." (PMID 36526722, 2022). "Hence, IL-7 SNPs exhibit potential for identifying patients at high risk of irAE and guiding therapeutic decision-making in melanoma cases." (PMID 40642097, 2025). "Therefore, our study aimed to evaluate the frequency of the IL-7 rs16906115 gene polymorphism and its potential association with irAE development among melanoma patients in the Turkish population receiving ICI therapy." (PMID 40642097, 2025). "Additionally, lower IL-7 levels were associated with specific genetic mutations and the overall cytokine profile in melanoma." (PMID 40636453, 2025). "The finding of improved disease-specific and overall survival in patients with melanoma carrying the risk allele in the TCGA dataset indicates that IL-7 plays a role in the natural history of melanoma and further highlights the potential therapeutic importance of this pathway." (PMID 36526722, 2022). "Specifically, the interleukin 7 (IL7) rs16906115 variant has recently been implicated in ICI-related toxicity in other malignancies, like melanoma, although its role in lung cancer remains less defined." (PMID 41753174, 2026). "Treatment with BRAFV600E or MEK1/2 inhibitors significantly reduced IL-7 secretion and lowered pERK and pMEK levels in BRAFV600E-mutated melanoma cell lines." (PMID 40636453, 2025). "In this single-center retrospective study, we investigated the potential utility of IL-7 rs16906115 polymorphism and lymphocyte stability index (LSI) in predicting susceptibility to irAEs among 96 melanoma patients treated with ICIs." (PMID 40642097, 2025). "In the B16-F10 melanoma model, viral co-expression of IL-7 plus IL-12 (hIL7/mIL12-VV), instead of using two separate viruses (hIL7-VV plus mIL12-VV), resulted in a complete response in 75% (6/8) animals compared to 25% (2/8) in the cont-VV control group." (PMID 40957993, 2025). "Recent studies involving an oncolytic vaccinia virus co-expressing IL-7 and IL-12 demonstrated potent antitumor efficacy across melanoma, colon, and lung cancer models." (PMID 40957993, 2025). "It was found that, although melanoma patients had increased levels of various cytokines and growth factors, IL-7 was reduced compared to healthy controls." (PMID 40636453, 2025). "Studies have shown that IL-7 can increase the number of anti-tumour immune cells in melanoma patients and improve the activity of these cells." (PMID 38675377, 2024). "A clinical trial found that combining IL-7 with immune checkpoint inhibitors significantly improved treatment response rates and survival in patients with advanced melanoma." (PMID 38675377, 2024). "In a lymphocytopenic mouse model of melanoma, IL-7-Fc treatment inhibited tumour growth by increasing the number of overtly metastatic CD8+ T cells in tumour tissue and tumour-draining lymph nodes." (PMID 38675377, 2024).
melanoma (continued). "Combinations of IL-7 with temozolomide for the treatment of glioblastoma and with atelizumab for the treatment of skin cancer, melanoma, and squamous cell carcinoma of the skin are under ongoing investigation." (PMID 38675377, 2024). "IL-7 promotes an anti-tumor response in glioma, melanoma, lymphoma, leukemia, prostate cancer, and glioblastoma." (PMID 39086683, 2023). "IL-7 presents antitumor effects in tumors such as glioma, melanoma, lymphoma, leukemia, prostate cancer, and glioblastoma." (PMID 38001643, 2023). "Recent studies have revealed that IL7 plays a significant role in glioma, melanoma and leukemia by contributing to anti-tumor effects through the release of cytokines, including IFNG, IL1A, IL1B, TNF, IL2 and IL4." (PMID 37958451, 2023). "A single intravenous administration of a 10-μg CBD–IL-12 monotherapy and a 2-μg CBD–IL-12 + IL-7–CBD combination therapy yielded equally significant extension in the survival of B16F10 melanoma–bearing mice when compared to phosphate-buffered saline (PBS)." (PMID 38019919, 2023). "This provides further independent evidence as to the importance of this allele in melanoma, inferring that, in addition to predisposing patients to ICB toxicity, B cell IL7 plays a role in the natural history of melanoma." (PMID 36526722, 2022). "Our previous study has been demonstrated that plasma IL-7 was lower in melanoma patients, which was insufficient for maintenance of Th17 cell activation." (PMID 35850640, 2022). "We previously showed that both are upregulated in FRCs of melanoma TDLNs and that IL7, a lymph node–critical cytokine is downregulated." (PMID 35362044, 2022). "In this study, the regulatory function of IL-7 to CD127 expression in melanoma patients was investigated." (PMID 35850640, 2022). "This was not consistent with our previous finding that in vitro regulation of Th17 response to IL-7 was STAT5 dependent in melanoma patients." (PMID 35850640, 2022). "Inhibition of PI3K abrogated IL-7-induced enhancement of CD8+ T cell cytotoxicity in both melanoma patients and healthy individuals." (PMID 35850640, 2022). "IL-7 inhibits melanoma growth by promoting the secretion of the cytokines IL-1β, IL-1α, and tumor necrosis factor-α (TNF-α) from monocytes." (PMID 36142322, 2022). "IL-7 promoted the cytotoxicity of peripheral CD8+ T cells from melanoma patients (P = 0.0004) and controls (P = 0.047), as well as tissue-infiltrating CD8+ T cells from tumor tissues (P = 0.023) and para-tumor tissues (P = 0.015)." (PMID 35850640, 2022). "In a lymphopenic murine melanoma model, IL7-Fc treatment led to the enhanced inhibition of tumor growth with an increased number of adoptively transferred CD8+ T cells in tumor tissue and tumor-draining lymph nodes." (PMID 34440787, 2021). "IL7-Fc, particularly in combination with rhIL-2, successfully suppressed the growth of B16-F10 melanoma in mice that received activated pmel-1 CD8+ T cells with prior lymphodepletion." (PMID 34440787, 2021). "Unexpectedly, the administration of IL7-Fc exacerbated the growth of B16-F10 melanoma in immune-competent B6 mice but synergistically suppressed tumor growth in mice administered 150 or 300 mkp CTX." (PMID 34440787, 2021). "In contrast, lower concentrations of BDNF, SDF-1α, MCP-1, Eotaxin, EGF, and IL-7 were observed in the serum of melanoma patients compared to healthy controls." (PMID 33574842, 2021). "Altogether, these data suggest that TIL1383I TCR-modified T cells generated following IL-7 culture have superior anti-melanoma activity in vivo on a per cell basis compared to cells generated following activation." (PMID 34172810, 2021). "At present, IL-7 application in immunotherapy has entered the clinical trial phase and achieved certain curative effects, including the cases of melanoma, lymphoma, and colon cancer." (PMID 34778046, 2021).